IGF1 (insulin like growth factor 1)
Diseases named in the same sentence as IGF1 in open-access papers (continued):
Sharing a sentence is not in itself a finding about the gene and the disease.
prostate carcinoma (continued). "In PC-3 prostate cancer cells, EL (40 μM; 24 h) inhibited IGF-1-induced cell proliferation by arresting cells at G0/G1-phase of the cell cycle and EL (60 μM; 20 h) suppressed migration." (PMID 28068967, 2017). "When IGF-1 was added to post-intervention serum to match the IGF-1 levels in the pre-intervention serum, the inhibition in prostate cancer cell growth was attenuated." (PMID 28481292, 2017). "Bicalutamide with tamoxifen have a synergistic inhibitory influence on prostate cancer growth and insulin-like growth factor 1 expression in prostate cancer patients." (PMID 28262798, 2017). "In the animal model, BA decreases serum prostate-specific antigen (PSA) levels by 88%, inhibits the LNCap tumour growth by 38% and reduces insulin-like growth factor-1 in nude mice injected with human LNCap prostate cancer cells." (PMID 28059072, 2017). "Circulating levels of IGF1 and IGFBP3 has been linked to all cause mortality in men with advances prostate cancer and risk of developing prostate cancer." (PMID 28966806, 2017). "Epidemiological studies have demonstrated a significant association between high IGF-1 levels, low IGFBP levels and increased risk of prostate cancer, spurring investigations into the effects of exercise on prostate tumor growth and cancer progression." (PMID 27349496, 2016). "The role of IGF1 in prostate cancer development is further supported by epidemiological studies showing an increase in serum IGF1 levels in patients who later developed the disease." (PMID 27285981, 2016). "For example, enhanced levels of the mitogen insulin-like growth factor 1 (IGF-1) and low levels of IGFBP-3 are associated with a higher risk of prostate cancer." (PMID 26912236, 2016). "Q itself has exhibited chemopreventive activities especially in prostate cancer through multiple mechanisms, including the induction of apoptosis and the inhibition of proliferation and insulin-like growth factor (IGF)-1 pathway." (PMID 27151407, 2016). "Although it appears that chronic RT beneficially alters factors in the IGF axis to reduce bioavailable IGF-1, larger RCTs are needed to ascertain the clinical impact of these results on the progression of prostate cancer." (PMID 27349496, 2016). "IGF‐1 is known to stimulate the growth of prostate cancer cells by inducing cell proliferation and inhibiting apoptosis." (PMID 27734632, 2016). "Exogenous IGF‐1 increased the invasive potential of the DU145 prostate cancer cell line, which was dependent on IGF‐1R, the ERK MAPK pathway, and the PI3K pathway." (PMID 27734632, 2016). "Intervention of IGF1/insulin-phosphatidylinositol 3-kinase-Akt signaling was reported to be of clinical value for prostate cancer." (PMID 27475327, 2016). "Previous studies have shown that IGF-1/IGF1R activation can promote EMT in prostate cancer cells and human mammary epithelial cells." (PMID 26554308, 2015). "Akt-dependent phosphorylation of filamin A at S2152 has been previously determined in prostate cancer cells and the IGF-1-treated MCF-7 cells." (PMID 25944616, 2015). "So far, IGF-1, IGF-1R, and IGFBP3 levels have only been shown to be possible but deficient prostate cancer risk markers." (PMID 24877145, 2014). "Along with IGF-1 signaling, androgen signaling is another pathway in which dietary fat intake can influence prostate cancer development." (PMID 25533015, 2014). "The main mechanisms of action seem to converge on the IGF-1 signaling pathway, leading to prevention or inhibition of malignant growth in prostate cancer cells." (PMID 25533015, 2014). "Based on the role played by IGF-1 in the progression of prostate cancer as well as other malignancies, strong interest exists in developing targeted therapies inhibiting the IGF-1 signaling pathway." (PMID 23823800, 2013). "In studies of acute exercise in healthy individuals, and also in prostate cancer patients undergoing androgen deprivation, serum levels of IL-6, GH and IGF-1 increase." (PMID 23861774, 2013).
prostate carcinoma (continued). "The insulin-like growth factor-1 (IGF-1) plays an important role in growth of prostate cancer (PCa) cells and facilitating the development and progression of PCa." (PMID 23530598, 2013). "In fact, the mitogenic and anti-apoptoptic effects of several adipokines, alone and combined, in prostate cancer cell growth (e.g. leptin, IL-6, insulin-like growth factor 1, IGF-1), seems to be limited to hormone-refractory prostate cancer cells." (PMID 22469146, 2012). "In prostate cancer cells, survivin expression has been shown to be regulated by IGF-1 stimulated Akt-mTOR signaling, which Is impaired upon simvastatin treatment." (PMID 22974127, 2012). "In prostate cancer cells, insulin-like growth factor-1 (IGF-1)-mediated mTOR pathway activation positively modulated survivin levels by increasing the translation of a survivin mRNA pool." (PMID 21470426, 2011). "Chemotaxis assays showed that IGF-1 stimulates androgen-independent DU145 prostate cancer cell migration and co-exposure to 4HPR completely abrogated the effect." (PMID 20537156, 2010). "IGF1, a growth factor, plays a role in the development of prostate cancer and has been reported as an indicator of advanced prostate cancer." (PMID 21060876, 2010). "Taken together, the up-regulation of the AR, IGF-1 signaling proteins, and their downstream effectors (ERKs) suggest a potential mechanism for prostate cancer development in the SV-40 Tag rat model." (PMID 19171036, 2009). "Elevated levels of IGF-1 and decreased levels of IGF-BP3 in the blood serum have been associated with an increased risk of advanced stage prostate cancer." (PMID 19171036, 2009). "Further work is necessary to elucidate additional elements of the complete mechanism for IGF-1 induction of prostate cancer invasion." (PMID 18598360, 2008). "During progression of prostate cancer, local levels of both IGF-1 and its receptor (IGF-1R) increase." (PMID 18182993, 2008). "We examined the invasive response of androgen independent DU145 prostate carcinoma cells to IGF-1 stimulation using Matrigel assays." (PMID 18598360, 2008). "The IGF-1/IGF-1R axis is well known to contribute to prostate cancer initiation, but its contribution to invasiveness and the downstream signalling mechanisms that are involved are unclear at present." (PMID 18598360, 2008). "This work identifies a specific effect of IGF-1 on the invasive capacity of DU145 prostate cancer cells, and furthermore delineates mechanisms that contribute to this effect." (PMID 18598360, 2008). "The role of IGF-1 in the progression of prostate cancer to an invasive and metastatic phenotype is still unclear, although it has been studied in other tumour types." (PMID 18598360, 2008). "The results from this study show that IGF-1 is a key regulator of the invasive potential of DU145 prostate cancer cells." (PMID 18598360, 2008). "For example, while serum levels of IGF-1 decrease with age, prostatic levels increase during prostate cancer progression." (PMID 18182993, 2008). "In the present study prostate-specific antigen (PSA) was also measured on the 141 men who developed prostate cancer and their controls at the same time as measuring IGF-1." (PMID 16804529, 2006). "The results for IGF-1 in relation to prostate cancer and BPH were adjusted for demographic and anthropometric factors, as well as for the other measured hormones." (PMID 9365156, 1997). "There was also some evidence for an interaction between high levels of testosterone and IGF-1 in relation to prostate cancer." (PMID 9365156, 1997). "Moreover, In prostate cancer, butyrate has also been shown to elevate circulating insulin-like growth factor-1 (IGF-1) levels, thereby activating the MAPK/PI3K pathway and promoting tumor progression." (PMID 41355959, 2026).
prostate carcinoma (continued). "Dietary factors, especially cow milk consumption and dairy products, which raise systemic IGF-1 levels and donate abundant amounts of essential branched-chain amino acids of the leucine prototype may affect prostate cancer development." (PMID 39941741, 2025). "Experimental data confirmed the implication of IGF-1 axis in prostate cancer development." (PMID 39941741, 2025). "IGF-1 has been found to promote the proliferation of prostate cancer cells and inhibit apoptosis." (PMID 39944628, 2025). "Hyperinsulinemia in T2D increases circulating insulin-like growth factor (IGF)-1 levels, activating downstream signaling cascades that enhance prostate cancer cell proliferation, survival, and metastasis via augmented glucose uptake and suppression of apoptosis." (PMID 41226058, 2025). "Beyond IGF-1 mediated signaling, prostate cancer progression is strongly supported by activation of the phosphatidylinositol 3-kinase (PI3K), protein kinase B (AKT), and mechanistic target of rapamycin (mTOR) pathway, a major pro-survival axis frequently upregulated in advanced disease." (PMID 41375042, 2025). "Since over 50% of men on long-term ADT will develop metabolic syndrome during their treatment, dietary therapy and low-protein intake may support the management of advanced prostate cancer through reductions of IGF-1 levels." (PMID 39954205, 2025). "Serum insulin and insulin-like growth factor-1 were significantly elevated in benign prostatic hyperplasia and prostate cancer group compared to controls with highest values in prostate cancer group (p-value <0.002 for insulin, <0.001 for insulin-like growth factor-1 and <0.014 for testosterone)." (PMID 39781138, 2024). "We have shown that lycopene acts synergistically with docetaxel to reduce the viability of human prostate cancer cells in an insulin‐like growth factor 1 (IGF‐1)‐dependent manner and to enhance the anti‐tumour efficacy of docetaxel in a xenograft mouse model of prostate cancer." (PMID 38515274, 2024). "In addition, GM have been shown to activate local MAPK and PI3K pathways via their - derived short - chain fatty acids, which in turn affect IGF1 signaling and ultimately prostate cancer growth." (PMID 39703512, 2024). "Other studies have proposed that zinc could induce insulin-like growth factor I (IGF-1), a hormone that has also been involved in prostate cancer progression." (PMID 38999774, 2024). "Numerous metabolic imbalances and interrelated pathways, including altered sex steroid hormones, serum insulin levels, and free insulin-like growth factor 1 levels may influence prostate cancer prognosis." (PMID 39180334, 2024). "The role of IGF1 in prostate cancer was also examined in a retrospective study comparing a cohort of men with acromegaly (N=2495) with a reference cohort (N= 4.3 million), revealing an increased risk of prostate cancer diagnosis (HR 1.33, [95%CI 1.09–1.63], p = 0.005)." (PMID 39840030, 2024). "Based on these results, we hypothesised that lycopene would act synergistically with docetaxel to kill prostate cancer cells in patients by the involvement of the IGF‐1 signalling axis." (PMID 38515274, 2024). "Also, the association of Nedd4 and IRS2 through monoubiquitination has been reported to activate IGF-1 signaling and induce cell proliferation in prostate cancer cells." (PMID 38272982, 2024). "Based on previous research, we hypothesize that the limited IGF-1 efficacy in prostate cancer in humans is probably due to the scarcity of reliable predictive biomarkers that forecast response to IGF-1R inhibition." (PMID 36831629, 2023). "However, based on previous research, prostate cancer can develop resistance to small molecule drugs through various mechanisms, such as the secretion of IGF-1 by adipocytes and the regulation of m6a methylation levels." (PMID 37932808, 2023).
prostate carcinoma (continued). "Using these genetic datasets, we also ran colocalization analyses to investigate whether the IGF1 gene region and prostate cancer share the same genetic signal to exclude the possibility of confounding by linkage disequilibrium." (PMID 35726641, 2023). "However, IRS2 only binds to USP15 after it is connected to the ubiquitin molecule, thereby blocking IGF1-dependent IRS2 phosphorylation to weaken IGF-I signaling in prostate cancer PC-3 cells." (PMID 35203682, 2022). "We, therefore, conclude that IGF-1 alters integrin subtypes in a concerted and fine-tuned manner, which may finally accelerate both prostate cancer growth and invasion." (PMID 35053528, 2022). "For example, in prostate cancer, gut microbiota could promote tumor proliferation through regulating systemic and local prostate IGF1 in the host, which was mediated by SCFAs." (PMID 36360204, 2022). "Since integrin β1 was altered similarly by IGF-1 and shown to down-regulate growth and invasion of both cell lines, functional blockade of β1 might be an option to treat prostate cancer once castration-resistance has been established." (PMID 35053528, 2022). "Although our Mendelian randomization results were unable to support previous evidence of an association between genetically predicted serum IGF-1 levels and prostate cancer risk, recent published Mendelian randomization studies reported a causal association of IGF-1 levels with prostate cancer." (PMID 35237523, 2022). "Thus, it seems that prostate cancer progression is controlled by a fine-tuned network between IGF-1-driven integrin-FAK signaling and the Akt-mTOR pathway." (PMID 35053528, 2022). "Evidence is provided that IGF-1 modulates the integrin α3, α5, αV and β1 expression pattern and distribution, which is associated with growth, adhesion and migration of DU145 and PC3 prostate cancer cells in vitro." (PMID 35053528, 2022). "Lycopene’s ability to suppress IGF-1 might be a major factor in preventing prostate cancer.In the field of targeted medication delivery, liposomes are the most widely used and thoroughly studied nanocarriers." (PMID 35903701, 2022). "Diosmetin treatment may modulate prostate cancer cell activation by IL-6 and IGF-1 and induces apoptosis downstream of Rictor signaling." (PMID 34682865, 2021). "IGF-1 has been shown to confer resistance to docetaxel in prostate cancer cells." (PMID 33768092, 2021). "Likewise, results of the Physicians’ Health Study revealed that the RR to develop prostate cancer was 4.3 among men in the upper quartile of IGF1 values compared to individuals in the lower quartile." (PMID 33182502, 2020). "There was also a suggestive association between genetically predicted IGF‐1 levels instrumented by the SNP in the IGF1 gene and prostate cancer, both in the PRACTICAL consortium (OR 1.33; 95% CI 1.02‐1.65; P = .01) and UK Biobank (OR 1.67; 95% CI 1.05‐2.65; P = .03)." (PMID 32717139, 2020). "Metformin has antineoplastic effects such as adenosine monophosphate-activated protein kinase (AMPK)-dependent suppression of androgen signaling pathway, and alterations of insulin-like growth factor-1 (IGF-1) signaling pathways that cause the growth and proliferation of prostate cancer." (PMID 32296640, 2020). "Thus, more studies are required on the specific tissue response of the IGF-1 axis to PRT in prostate cancer." (PMID 32056047, 2020). "Milk intake may increase proliferation of cancer cells through elevated insulin-like growth factor-I (IGF-1), which is linked to an increased risk of prostate cancer." (PMID 31315238, 2019). "However, among men with prostate cancer, the mean IGF‐1 levels of those with low (GS ≤ 6), intermediate (GS = 7), and high surgical GS (GS ≥8) were 151.7, 144.1, and 132.9 ng/mL, respectively (P < 0.001)." (PMID 29992746, 2018).
prostate carcinoma (continued). "In addition, meta-analysis of published research investigating the association of IGF-1–IGF-2 and their binding proteins IGFBP-1–6 with prostate cancer confirmed that elevated circulating level of IGF-1 positively correlates with higher prostate cancer risk." (PMID 29487568, 2018). "Higher serum levels of IGF-1 and lower levels of IGFBP-3 have been associated with increased risk of aggressive prostate cancer although higher levels of IGFBP-3 have been observed in prostate tumor cells compared to benign cells, and are associated with higher cancer recurrence." (PMID 28417914, 2017). "One hypothesis is that indirect insulin lowering effect may have an anti-neoplastic effect as elevated insulin and insulin like growth factor − 1 (IGF-1) levels play a role in prostate cancer development and progression." (PMID 28732480, 2017). "Leptin, an hormone activating the same pathway of insulin and IGF-1, stimulate survival of prostate cells hormone independent and increased blood levels of leptin were observed in patients with an aggressive biology of prostate cancer." (PMID 28389628, 2017). "The potential data does not suggest a direct causative role for IGF‐1 signaling in the progression and invasiveness of prostate cancer." (PMID 27734632, 2016). "DHT appears to work synergistically with IGF-1 to enhance prostate cancer progression." (PMID 26977321, 2016). "The effect of IGF‐1 on prostate cancer cell lines has been extensively explored." (PMID 27734632, 2016). "Indeed, IGF-1 is able to stimulate androgen-sensitive and androgen-independent prostate cancer in human cell lines." (PMID 27349496, 2016). "In human prostate cancer cells, IGF-1 upregulates ZEB1 and drives EMT." (PMID 25436001, 2015). "Re-expression of CAMK2N1 in prostate cancer cells reduced cellular proliferation, arrested cells in G0/G1 phases, and induced apoptotic cell death accompanied by down-regulation of IGF-1, ErbB2, and VEGF downstream kinases PI3K/AKT, as well as the MEK/ERK-mediated signaling pathways." (PMID 25003983, 2014). "Certain data showed that the PSA/IGF-1 ratio could differentiate between prostate cancer and BPH but was met with criticism." (PMID 24877145, 2014). "Culig and colleagues demonstrated that, in human prostate cancer cells, various growth factors including insulin-like growth factor 1 (IGF-I), keratinocyte growth factor (KGF), and epidermal growth factor (EGF) directly activate the AR in the absence of androgens." (PMID 23896594, 2013). "Recently, in vitro and in vivo prostate cancer models have demonstrated that lycopene increases the antineoplastic effects of docetaxel by inhibiting the activation of IGF-1R through the inhibition of IGF-1 stimulation and increased IGFBP3 expression." (PMID 23970935, 2013). "In one study, IGF1 was identified as one of the top ten genes probable to drive prostate cancer." (PMID 22880013, 2012). "Furthermore, we evaluated the role of sex steroid receptor and IGF-1 signaling proteins, cell proliferation, and apoptosis in the development of prostate cancer in this model." (PMID 19171036, 2009). "Therefore, IGF-1 in the prostate tissue appears to be an important protein involved in prostate cancer development in this model." (PMID 19171036, 2009). "In prostate cancer cells IGF1 regulates expression of αvβ3 integrin via activation of PKB/Akt." (PMID 19774072, 2009). "This is the first study, to our knowledge, showing that the addition of exogenous IGF-1 to prostate cancer cells results in a significant increase in invasive potential, and that these effects are reduced by inhibiting IGF-1R, the MAPK pathway or the PI3-K pathway." (PMID 18598360, 2008). "This suggestive data, however, does not establish a direct causative role for IGF-1 signalling in the promotion of prostate cancer progression to an invasive phenotype." (PMID 18598360, 2008).